IL9 (interleukin 9)
Diseases named in the same sentence as IL9 in open-access papers (continued):
Sharing a sentence is not in itself a finding about the gene and the disease.
Rett syndrome (1 paper, 2023). A severe neurodevelopmental disorder affecting the central nervous system. "Patients diagnosed with Rett syndrome have exhibited significantly elevated levels of IL-9 in their serum compared to individuals in the control group." (PMID 38002479, 2023).
Salmonella Infections (1 paper, 2010). Infections with bacteria of the genus SALMONELLA. "Overall, these data illustrate that the IL-4 and IL-9 signaling pathway associated with TH2 immune response was activated by pathogenic Salmonella infection in colon mucosa." (PMID 21172007, 2010). "Hence, IL-4 and IL-9 signaling pathway activated in mouse mucosa with Salmonella infection provides more comprehensive information about how the Th2 immune system interplays with signaling transducers in colon mucosal inflammation." (PMID 21172007, 2010).
sarcopenia (1 paper, 2022). Progressive decline in muscle mass due to aging which results in decreased functional capacity of muscles. "Only lower IL-9 level associated with presence of myosteatosis, sarcopenia, or both muscle abnormalities (p = 0.037)." (PMID 35566781, 2022). "Sarcopenia showed a trend of a negative association with serum Hb level, and myosteatosis negatively associated with IL9, had a trend of negative association with INFg, and a trend of positive association with NLR." (PMID 35566781, 2022).
scleroderma (1 paper, 2024). Scleroderma is a rare autoimmune connective tissue disorder characterized by abnormal hardening of the skin and, sometimes, other organs. "The role of IL-9 in RA and scleroderma is less clear: IL-9 may promote wound healing and reduce fibrosis in some contexts, but IL-9 is also reported to induce fibrosis and worsen joint inflammation." (PMID 38825637, 2024).
scrub typhus (1 paper, 2023). Scrub typhus is a rare dust mite-borne infectious disease caused by the Orientia tsutsugamushi bacterium and characterized clinically by an eruptive fever which is potentially serious. "Ot infection can also slightly increase serum IL-5, IL-9, IL-13, and GM-CSF levels; however, their roles in scrub typhus remain unclear." (PMID 38091346, 2023).
septic shock (1 paper, 2013). Shock caused by infection; frequently caused by gram negative bacteria, although some cases have been caused by other bacteria, viruses, fungi, and protozoa; characterized by fever, chills, tachycardia, tachypnea, and hypotension. "Less studied in septic shock are the TH2 cytokines IL4, IL5, IL9 and IL13." (PMID 24244449, 2013).
skin infection (1 paper, 2019). An inflammatory process affecting the skin, caused by bacteria, viruses, parasites, or fungi. "Because we observed that a substantial number among skin-derived T cells is able to produce IL-9, it is tempting to speculate that IL-9–producing T cells might indeed contribute to controlling Candida skin infections." (PMID 30807238, 2019).
sporotrichosis (1 paper, 2025). The commonest and least serious of the deep mycoses, characterized by nodular lesions of the cutaneous and subcutaneous tissues. "We found that IL-18R was elevated in the lesional skin and S. globosa-infected CD4+T cells in this study, particularly within the Th2 subset; however, whether IL-9 sensitizes Th2 cells to IL-18 signals in sporotrichosis needs further investigation." (PMID 40489556, 2025).
steatosis (1 paper, 2024). Increased lipid within the cytoplasm of cells. "Most of the measured cytokines had similar concentrations, except for IL-9, IL-10, IL-13 and IL-22, which were significantly lower in patients with steatosis." (PMID 39200991, 2024). "In this study, we focused on the role of IL-22, IL-9, IL-10 and IL-13 in CHC, particularly in the context of steatosis." (PMID 39200991, 2024). "Reduced concentrations of IL-9 in the sera of patients with steatosis and a negative correlation between CAP and IL-9 levels shown in this study may suggest that reduced levels of IL-9 and Th9 cells may contribute to the microenvironment favoring the development of steatosis." (PMID 39200991, 2024).
Strongyloides infection (1 paper, 2014). "We analyzed the impact of IL-9 during Strongyloides infection and showed that administration of IL-9 reduced parasite burden while neutralization of IL-9 reciprocally increased parasite burden in the small intestine of S. ratti-infected BALB/c and C57BL/6 mice." (PMID 24516385, 2014).
thymic carcinoma (1 paper, 2025). Thymic carcinoma (TC) is a type of thymic epithelial neoplasm characterized by a high malignant potential. "Unexpectedly, thymic carcinoma cases exhibited a distinct cytokine milieu skewed toward type 2 inflammation, with increased levels of IL-4, IL-5, IL-9, and IL-13." (PMID 41368637, 2025). "Serum IL-18 levels were elevated—particularly in thymic carcinoma—and correlated with higher concentrations of type 2 cytokines (IL-4, IL-5, IL-9, IL-13)." (PMID 41368637, 2025).
thyroid cancer (1 paper, 2024). "In breast and thyroid cancer, IL-9 has been implicated in promoting cell growth and contributing to tumor progression." (PMID 39334861, 2024).
toxic epidermal necrolysis (1 paper, 2025). Toxic epidermal necrolysis (TEN) is an acute and severe skin disease with clinical and histological features characterized by the destruction and detachment of the skin epithelium and mucous membranes. "Severe cutaneous adverse reactions, including DRESS, SJS, and toxic epidermal necrolysis (TEN), involve pathogenic mechanisms in which cytotoxic CD8+ T lymphocytes, as well as certain pro-inflammatory eosinophil promoting cytokines (such as IL-4, IL-5, IL-9, IL-13), play a role." (PMID 40869188, 2025).
toxocariasis (1 paper, 2025). A parasitic infection caused by worms found in domestic animals. "In contrast, in toxocariasis, Th2 cells are involved; they secrete IL-4, IL-5, IL-9, IL-10, and IL-13 and promote type 2 immunity, characterized by high antibody titers." (PMID 40943043, 2025).
urticaria (1 paper, 2024). A vascular reaction of the skin characterized by erythema and wheal formation due to localized increase of vascular permeability. "IL-9 and apo A-IV might be potential novel biomarkers to predict urticaria severity." (PMID 38482455, 2024). "Baseline urticaria severity demonstrated a statistically significant positive and negative correlations with IL-9 (ρ = 0.277, P = 0.007) and apo A-IV (ρ = −0.271, P = 0.008) levels, respectively." (PMID 38482455, 2024).
vaginal candidiasis (1 paper, 2018). "Given that IL-9 contributes to inflammation in the early phase of vaginal candidiasis, we asked whether a timely administration of an IL-9 neutralizing antibody could ameliorate vaginal pathogenesis." (PMID 30515173, 2018).
visceral leishmaniasis (1 paper, 2020). A severe form of leishmaniasis characterized by irregular bouts of fever, substantial weight loss, swelling of the spleen and liver, and anemia (which may be serious). "IL-9 is a susceptibility factor in Leishmania infection by promoting detrimental Th2 responses, and elevated levels of IL-6 have been correlated with a high severity of visceral leishmaniasis." (PMID 32867338, 2020).
vitiligo (1 paper, 2021). Generalized well circumscribed patches of leukoderma that are generally distributed over symmetric body locations and is due to autoimmune destruction of melanocytes. "Interestingly, the same study showed the highest frequency of CD4+/CD8+ CLA+ T cells producing IL-9 in patients with vitiligo in comparison with patients with AD, PSO, and AA and HC, pointing out for the first time a possible role for IL-9 on the physiopathology of vitiligo." (PMID 33833765, 2021).
tumor (243 papers, 2010 to 2025). "Greater IL9+ cell infiltration in the tumor tissue was associated with worse prognosis, greater frequencies of Treg cells, and decreased cytotoxic capability of CD8+ T cells and NK cells in patients with muscle-invasive bladder cancer." (PMID 41019045, 2025). "Clinically, CA125, CA199, and IL-9, identified as risk factors for poor prognosis, align with previous research on tumor markers and inflammatory cytokines in tumor progression." (PMID 41040659, 2025). "Mast cells stimulate the migration of MDSCs toward the tumor, causing these cells to produce IL-17, which, in turn, attracts Tregs and induces them to produce the enigmatic cytokine IL-9." (PMID 41200621, 2025). "Tumor-infiltrating Th9 lymphocytes release the characteristic cytokine IL-9, which has been implicated in various immune and inflammatory diseases, including parasitic infections, allergies, and lymphoma." (PMID 38840908, 2024). "One particular cytokine that we observed differential effects in was IL-9, which was elevated in serum of the anti-PD-1-treated group and associated with decreased tumor burden in E0771 ICI monotherapy study." (PMID 39623404, 2024). "In a mouse model of colitis-associated cancer, IL-9 suppressed tumour growth through CD8+ T cell activation." (PMID 37455828, 2023). "To investigate the mechanism underlying the antitumor effect of IL9 on the macrophage-enriched tumor model, we collected tumor masses after euthanizing the tumor-bearing mice (n = 4) on day 15 after tumor implantation." (PMID 36968220, 2023). "This underlines that not only a high stromal IL9 expression is beneficial, but the concentration must apparently be higher than in the tumor epithelium." (PMID 36131941, 2022). "Deficiency of IL-9 or inactivation of PU.1 in T cells led to impaired tumour growth in vivo, suggesting a protumoral role of Th9 cells." (PMID 35793807, 2022). "Consistent with the phenotype discovered for IL-9 deficient mice, intraperitoneal anti-IL-9 antibody treatment in WT mice resulted in increased body weight and an increased tumor rejection as compared to control IgG-treated WT animals." (PMID 35514957, 2022). "Th9 cells are relatively newly described and poorly characterized cells, with IL-9 as their hallmark cytokine, with multiple functions, such as promoting immune tolerance, enhancing immune response, and anti-tumor activity." (PMID 35935994, 2022). "With regard to the rs2069885 polymorphism in the gene encoding IL-9, it was also studied in inflammatory and neoplastic diseases." (PMID 36361964, 2022). "In contrast, IL-5, IL-17A, IL-21, IL-22, and TGFβ concentrations in the tumour tissue of IL-9 knockout mice were significantly reduced compared with wild-type mice, indicating that IL-9 controls the production of Th2- and Th17-associated cytokines." (PMID 35793807, 2022). "This is a potential explanation for why loss of IL-9 signaling hinders the pro-tumor effects of lung macrophages." (PMID 35778404, 2022). "IL-9 mRNA levels in tumours showed a marked correlation with the Th9-associated transcription factors Irf4, Gata3, and Spi1, as well as with Socs3." (PMID 35793807, 2022). "In this review, we mainly summarize the different roles and underlying mechanisms of IL-9 and IL-9-producing cells (Th9 cells, Tc9 cells, Vδ2 T cells, and mast cells) in tumor immunity." (PMID 32228589, 2020). "Further experiments showed that the neutralization of IL-9 caused the downregulation of Tregs and mast cells, resulting in the inhibition of tumor growth." (PMID 32508847, 2020). "CD4+ helper T cells producing IL-9 (Th9) have been implicated in anti-tumor immunity, with Th9 differentiation inducible in vitro via IL-4 and TGFβ treatment." (PMID 30914642, 2019). "In line with this, the anti-tumor effects of recombinant IL-9 administration were conserved in tumor-bearing Rag1-deficient mice, suggesting that other immune effectors are involved in the anti-cancer effects observed." (PMID 27832300, 2017).
tumor (continued). "Tumor infiltrating CD4+T cells isolated from the SIRT1-deficient groups had a higher IL-9+ ratio than the WT group." (PMID 27589682, 2016). "Similarly, we found higher levels of IL-9 in the tumor tissues to be associated with higher T cell infiltration." (PMID 40497965, 2025). "IL-9 was the only plasma analyte whose change from pre-treatment to pre-cycle 2 was significantly associated with response, linking a change in a peripheral blood population with the therapeutic effect on the tumor." (PMID 38789460, 2024). "The increase in IL-9 expression may be associated with the promotion of inflammatory and immunosuppressive processes, which favor tumor development and progression." (PMID 39334861, 2024). "Evaluating the role of IL-9 on cancer development in a mouse model of BC (HER2+ and TN models) also demonstrated that IL-9 deficiency through neutralizing antibodies or deleting endogenous IL-9 led to priming host tumor-specific T-cells, acquiring immunologic memory, and the early rejection of BC." (PMID 37835465, 2023). "Given the possibility that intratumoral IL9 is associated with the accumulation of antitumor immune cells in the tumor mass, we sought to determine which chemotactic chemokines could play an important role in our experimental model." (PMID 36968220, 2023). "Conversely, some studies have found that IL-9 may instead promote tumorigenesis as seen in a heterotypic CT26 implant model of CRC where genetic IL-9 deficiency reduced tumour growth." (PMID 37455828, 2023). "In contrast, Il9-deficient mice show dramatically less tumor burden in a tumor metastasis model." (PMID 35778404, 2022). "Previous studies have shown that IL-9 affects the oxidative burst of human blood monocytes and AMs but little is known about how IL-9 affects the phenotype and plasticity of lung macrophages or whether this might be linked to tumor progression." (PMID 35778404, 2022). "Indeed, treatment of IL-9 knockout mice with hyperIL-6 abrogated the protective effects of IL-9 deficiency and led to a marked tumour growth, thereby demonstrating that IL-9 is an important regulator of IL-6 trans-signalling effects in colorectal neoplasias." (PMID 35793807, 2022). "Because the IL-9/IL-9R axis is important for reducing lipid peroxidation and ferroptosis in Tc9 cells in vitro, we investigated whether IL-9 or IL-9R deficiency could affect the Tc9 cells’ ability to persist and control tumor growth in vivo." (PMID 35192544, 2022). "Another cytokine that has been associated with an antitumor response is IL-9, which favors the activation of cytotoxic T lymphocytes by recruiting dendritic cells to tumor tissues for the presentation of these antigens and the subsequent elimination of malignant cells." (PMID 36296703, 2022). "Additionally, high NLR has been associated with elevated infiltration of tumour-associated macrophages in the tumour microenvironment and elevated circulating cytokines (IL-1ra, IL-6, IL-7, IL-8, IL-9, IL-12, IFN-γ, IP10, MCP-1, MIP-1β, and PDGF-BB)." (PMID 36077723, 2022). "Peripheral blood CD8+ T cells had high expression of IL9 and low expression of gene sets associated with lipid peroxidation and ferroptosis activation, while tumor-infiltrating CD8+ T cells showed the opposite trend." (PMID 35192544, 2022). "Notably, IL-9-deficient mice acquired immunologic memory, which actively protected them from residual disease and tumor re-challenge, an effect that is linked to the activation of CD8-positive T cells." (PMID 31637216, 2019). "Conversely, IL-9 and Th9 cells are rather associated with an anti-tumor immunity." (PMID 29963229, 2018). "Therefore, we focused on the influence of IL-6 on tumour development in IL-9-deficient animals." (PMID 35793807, 2022).
tumor (continued). "As expected, tumor-infiltrating Il9–/– or Il9r–/– Tc9 cells had higher lipid peroxidation and cellular iron levels, and lower mitochondrial activity than WT Tc9 cells, indicating that IL-9– or IL-9 signaling–deficient Tc9 cells undergo enhanced ferroptosis in the TME." (PMID 35192544, 2022). "The role of IL-9 in tumor development and progression is complex due to its diverse functions, and it varies depending on the type of cancer." (PMID 39852828, 2025). "Histologically, the presence of goblet cells in the mucosal epithelium of the upper airway is closely associated with the production of cytokines such as IL‐13, IL‐8, and IL‐9, which play a role in inflammatory pathways and consequently tumor progression." (PMID 40867038, 2025). "In summary, our study highlights that IL-6, VEGF, PDGF-BB, IP-10, MCP-1, and IL-9 exhibit complex and often context-dependent roles in tumours, making them both potential biomarkers and therapeutic targets." (PMID 40733274, 2025). "In tumor immunology IL-9 is considered a “double-edged sword” because its pleiotropic effects can lead to both pro- and anti-tumor effects." (PMID 40497965, 2025). "We examined the activity of EEP PL and quercetin on the production of IL-6, VEGF, PDGF-BB, IP-10, MCP-1 and IL-9 by the CCF-STTG1 cell line present in the tumour microenvironment of CNS." (PMID 40733274, 2025). "Here, the deletion of IL-9 in T cells or the deactivation of PU.1 resulted in impaired tumor growth, suggesting a pro-tumoral role for PU.1+ Th9 cells." (PMID 40895524, 2025). "IL-6, VEGF, PDGF-BB, IP-10, MCP-1, and IL-9 exhibit complex, often context-dependent functions in tumours, making them potential biomarkers and therapeutic targets." (PMID 40733274, 2025). "Recombinant IL9 activation increased the cytotoxicity of tumor-specific mice CD8+ T cells, whereas blocking IL9-signalling decreased the production of granzyme B and perforin in human CD8+ T cells." (PMID 41019045, 2025). "The STING ligand 2’3’-cGAMP increases IL-9 in an mTOR-dependent manner, enhancing anti-tumor immunity." (PMID 41030439, 2025). "In turn, in muscle-invasive bladder cancer (MIBC), the presence of IL-9-producing Th cells in the tumor microenvironment was correlated with an exhausted phenotype of CD8+ T cells." (PMID 39325360, 2025). "Studies suggest that IL-9 promotes tumour growth by both inhibiting apoptosis and enhancing the proliferation of malignant cells." (PMID 39325360, 2025). "In vivo studies have shown that immunization with Dectin-1-activated DCs leads to significant tumor regression, primarily mediated by Th9 cells and IL-9 production." (PMID 41163402, 2025). "The analysis revealed that cytokines, including IFN-γ, IL-1ra, IL-8, M-CSF, MCP-1, MIP-1α, and SCGF-β, were associated with tumor height, while β-NGF, GRO-α, IL-5, IL-9, MIP-1β, TNF-β, and VEGF were linked to tumor diameter." (PMID 41048959, 2025). "The inclusion of IL-9 significantly elevated the vaccine-induced specific T cell response and enhanced anti-tumor efficacy." (PMID 39852828, 2025). "In cancer, IL-9 plays dual roles acting as either a tumor suppressor or promoter depending on the tumor type." (PMID 41030439, 2025). "Higher levels of CXCL10, IL-9, and CCL4 in the tumor tissues were found to be associated with higher numbers of T cells in direct contact with tumor cells." (PMID 40497965, 2025). "have revealed that CD8+ Tc9 subset with high IL‐9 secretion exhibits robust anti‐tumour activity and longevity, making it a promising candidate for immunotherapy." (PMID 40045458, 2025). "Conversely, the use of IL-9-blocking antibodies reversed this tumor growth inhibition, enhancing tumor growth in wild-type mice." (PMID 41148223, 2025). "This cascade, culminating in IL-9 production, appears to promote the survival of pro-tumor mast cells in the TME." (PMID 41200621, 2025).